LRRC63 (leucine rich repeat containing 63)
Synonyms: RP11-139H14.4
Tractability: No criterion of Open Targets' tractability assessment is met for any kind of drug.
Gene: Protein-coding gene on chromosome 13 (46,211,928 to 46,277,115, forward strand). Ensembl gene ENSG00000173988.
Subcellular location (Human Protein Atlas): Golgi apparatus
Gene Ontology:
Biological process: intracellular signal transduction
Genetic constraint (gnomAD): Loss-of-function variants: 28 observed, 29.47 expected, observed/expected ratio (o/e) 0.95, 90% interval 0.7 to 1.3. The upper end of that interval is the gene's LOEUF score, 1.3, which puts it in group 5 of 6, group 1 being the genes least tolerant of losing a copy. Missense variants: 412 observed, 444.16 expected, observed/expected ratio (o/e) 0.93, 90% interval 0.86 to 1.01. Synonymous variants: 130 observed, 148.42 expected, observed/expected ratio (o/e) 0.88, 90% interval 0.76 to 1.01.
Homologues: Orthologues: chimpanzee LRRC63 (98% identical), macaque LRRC63 (89% identical), dog LRRC63 (60% identical), pig LRRC63 (59% identical), rabbit LRRC63 (58% identical), mouse Lrrc63 (53% identical), rat Lrrc63 (51% identical).
Diseases named in the same sentence as LRRC63 in open-access papers:
LRRC63 is named in the same sentence as 1 disease in open-access papers, as found by Europe PMC text mining. Sharing a sentence is not in itself a finding about the gene and the disease.
LRRC63 shares sentences with these, for which no sentence is quoted: neurological disease (1 paper).